IL6 (interleukin 6)
Diseases named in the same sentence as IL6 in open-access papers (continued):
Sharing a sentence is not in itself a finding about the gene and the disease.
infection (continued). "ALVAC immunization within the first 24 hours of infection increases the production of the pro-inflammatory cytokines IL-1, IL-6, and IL-10 by 20–50-fold." (PMID 32163525, 2020). "Nonetheless, in vivo IFN-γ neutralization in IL-17RA KO mice (at days 3 and 6 post-infection) increased skin production of Th17-lineage cytokines (IL-22, IL-17, IL-1β, IL-6) and significantly inhibited fungal growth." (PMID 33343578, 2020). "In contrast, IL-6 concentrations continued to rise over the course of this early stage of infection." (PMID 31937782, 2020). "IL-6 is a pleotropic cytokine produced in response to tissue damage in several disease and infections." (PMID 33244370, 2020). "The in vitro study of EGYVIR extract against SARS-CoV-2 on Huh-7 cell lines, revealed the potential role of NF-kβ/TNFα/IL-6 during the infection process." (PMID 33206688, 2020). "GEM treatment (100 μM) of BMDMs dramatically suppressed the expression of a variety of inflammatory cytokines and chemokines (Il6, Il12p40, Il1b, Cxcl10, and Cxcl5) at 18 h after infection." (PMID 32155958, 2020). "Independent transcriptome datasets from infection models revealed that IL6 is the major cytokine differentially expressed after infection with SARS- CoV2." (PMID 32826388, 2020). "Here, we demonstrate that despite enhanced bacterial numbers during the early phase of the infection, IL-6 KO mice showed reduced spleen weight at 1 week post-infection." (PMID 33322581, 2020). "Seven cytokines showed infection-dependent increases in localized tissues: IL-1α, IL-1β, IL-6, IL-8, MCP-1, MIP-1α, and MIP-1β (p < 0.05)." (PMID 32867801, 2020). "We observed a smaller increase of iNos and Il6 transcripts for septic mice compared to sham-operated mice after the secondary infection." (PMID 32425929, 2020). "C5a is a potent signalling molecule that activates immune cells to release cytokines, including tumour necrosis factor (TNF), interleukin (IL)‐1β, IL‐6 and IL‐8 within hours of infection." (PMID 34192268, 2020). "Interferons, like IFN-α, IFN-β, and IFN-γ, and other cytokines, like interleukin 6 (IL-6), IL-8, and IL-12, have been seen to be involved in recovering from the infection." (PMID 33327628, 2020). "Our results demonstrated that IL-6 KO mice showed reduced spleen weight at 1 week post-infection, and similar spleen weight at 6 weeks post-infection compared to wild-type infected mice." (PMID 33322581, 2020). "It was proven that during infection, secreted IL-2 and IL-6 play a potential role in apoptosis and T cell survival through increased transcription and translation of the FasL gene." (PMID 32349424, 2020). "On day 42 of infection, the concentration of IL-6, TNF, IL-12p40 and IFNγ were significantly reduced in doramapimod-treated animals (white and black bars)." (PMID 32788581, 2020). "In the context of infection and inflammation, the transcription of the Fpn-regulatory hormone hepcidin is induced by IL-6-activated JAK/STAT signaling." (PMID 32616918, 2020). "Interleukin 6 (IL-6) is one of the markers of immune system activation indicating existent infection and inflammation." (PMID 33304877, 2020). "It had been reported that the expression of inflammatory cytokine genes like TNFα, IL-1β, IL-6 and IL-8 were up-regulated by the infection of Ich in rainbow trout larvae." (PMID 32295151, 2020). "Infection with Fowl Adenovirus Group 4 (FAdV-4) is reported to increase the expression of IL-6, IL-8 and TNF-α and produce tissue damage in lymphoid organs, principally through apoptosis." (PMID 32674433, 2020). "The infection with coronavirus induces a cytokine storm and interleukin-6 is a major initiator of the acute phase response." (PMID 33332362, 2020). "Specifically, MAP infection in macrophages induced Notch-1 and IL-6 signaling and resulted in the hijacking of MCL-1 causing apoptosis and persistence infection." (PMID 33072191, 2020). "IL-6 not only regulates reaction to infection or injury but also relates to immune disorders and cancers." (PMID 32391256, 2020).
infection (continued). "Some IL-6-dependent outcomes help stave off infections such as directing neutrophil migration to the infection site, increasing CD8+ T cell cytolytic capacity, and regulating antiviral thermostatic reactions." (PMID 33194450, 2020). "Recent studies have shown that interleukin-6 (IL-6) has a higher specificity for detecting the presence of infection; however, this test remains relatively expensive and inaccessible to the average surgeon." (PMID 32089975, 2020). "During the whole course of infection, the bacterial load in the lungs, spleen and liver of IL-6−/− mice was comparable to C57BL/6 mice." (PMID 33375150, 2020). "Heightened concentrations of IL-6, TNFα, and IL-4 support previous pathogen exposure and a possibility of current infection." (PMID 32849592, 2020). "Although il-6 mRNA remained elevated for several days in the spleen after infection, elevated serum IL-6 protein was primarily detected at day 2 postinfection." (PMID 32487756, 2020). "In the present study, the expression of Th17-related mRNA showed that IL-23 and IL-6 were significantly activated early during infection, while IL-1β and IL-17 were highly activated after 6 h post infection." (PMID 33520738, 2020). "Overexpression of MARCH2 increased virus replication and reduced secretion of IFN‐β and IL‐6 in response to infection by VSV‐GFP, PR8‐GFP, or HSV‐GFP." (PMID 32935379, 2020). "Interleukin-6 (IL-6) has the roles to support host immune response to infections as a pleiotropic cytokine." (PMID 32014014, 2020). "In Candida albicans or Malassezia epicutaneous infections, IL-6- or IL-23-producing LC migrate and induce an antigen-specific Th17 response by 7–10 days post-infection." (PMID 33343578, 2020). "Under normal circumstances, interleukin-6 (IL-6) is secreted transiently by myeloid cells as part of the innate immune response to injury or infections." (PMID 33071786, 2020). "This further implies that infiltrating immune cells are the likely source of pro-inflammatory cytokines such as IL-6 and TNFα reported to be elevated in patient sera later during infection." (PMID 33284849, 2020). "The levels of inflammatory cytokines in mouse sera, such as IFN-γ, IL-6, and IL-12, peaked at about 6 weeks post-infection, which indicated that the mice had mounted an acute inflammatory response." (PMID 33330140, 2020). "An important aspect of the host defense response is the secretion of proinflammatory cytokines like tumor necrosis factor (TNF), interleukin-6 (IL-6), and IL-1 that facilitate immune cell recruitment to the site of infection." (PMID 32229615, 2020). "IL-6 is a multifunctional cytokine that plays an important role in the response to infection or systemic inflammation, often referred to as ‘acute phase reactions’." (PMID 32971939, 2020). "Antigen-specific TH17 cells were still generated in IL-6−/− mice after infection with Mtb, although their frequency again tended to be reduced when compared to C57BL/6 mice." (PMID 33375150, 2020). "On day 5 post-infection, both oral administration of valine and intraperitoneal injection of CoA can significantly reduce virus titers and levels of IL-1β, IL-6, and IL-10 of the lungs and at the same time upregulate IFN-β and IFN-γ of the lungs." (PMID 32345342, 2020). "During infection by B. abortus, IL-6 secretion contributes to host resistance, controlling the bactericidal activity of macrophages." (PMID 32765455, 2020). "IL-6 production was also significantly increased after MEDI5395 (P < 0.001 at MOI 1) infection compared with mock-infected controls." (PMID 32088771, 2020). "As infection persisted, we observed an increase in the cytokine TNFα; a decrease in the cytokine IL-6; an increase in T-cell priming co-receptors CD80/86, and MHCII; and a decrease in CD103 and IL-10." (PMID 32635236, 2020).
infection (continued). "To confirm an increased pro-inflammatory status of the human lung epithelial cells upon super-infection, we analyzed the mRNA expression of different representative pro-inflammatory cytokines and chemokines (IL-6, IL-8, TNFα, IL-1β, and IFN-γ) in detail." (PMID 33333815, 2020). "RSV infection of SIRT1-/- BMDC induced significantly higher Il1β, Il6 and Il23 expression early in the infection as compared to WT+RSV." (PMID 32106265, 2020). "IL6 has also several effects on the body, controlling several processes in the response to infection." (PMID 33182721, 2020). "When mice were treated with anti-CD20 mAb prior to infection, significant decreases in the levels of IL-6- and IL-17A-producing lymphoid cells were observed." (PMID 32398312, 2020). "Here, we investigated the impact of IL-6 for the development of a TH17 immune response after infection with Mtb by use of IL-6−/− mice." (PMID 33375150, 2020). "After infection, activated macrophages with the proinflammatory phenotype produce a number of cytokines including IL-6, which drive inflammatory and anti-microbial responses affecting the spread of bacterial infections in the organism." (PMID 33425777, 2020). "IL6 plays a central role in the acute inflammatory response, and a long duration of its release can also be used to assess the severity of infection and judge prognosis." (PMID 32754224, 2020). "Further analysis of the spatial proteome by MALDI-MSI showed strong expression of IL-6 in the urothelium and local inhibition of this molecule reduced macrophage migration into the urothelium and aggravated the infection." (PMID 32112048, 2020). "In the early stage of infection, IL-6, G-CSF, and IL-13 levels were high in the A/Zhejiang/DTID-ZJU01/2013(H7N9) and A/Guangdong/GZ8H002/2017(H7N9) infection groups." (PMID 32267217, 2020). "In accordance with other studies, BALFs from patients with severe/critical infection showed much higher levels of IL-8, IL-6, and IL-1β expression than those from patients with moderate disease." (PMID 33062077, 2020). "Taken together, these data demonstrate that the decrease of IL-6 delays spontaneous formation of infection-driven B-ALL in Pax5+/- mice." (PMID 33154497, 2020). "The expression trend of pro-inflammatory factor IL-6 was more complex, peaking on the first day after infection, then decreasing, and increasing again on the 4 dpi." (PMID 31947624, 2020). "In children aged 3 to 17 years with H1N1 influenza virus infection and severe clinical manifestations of the infection, IL-1β and IL-6 plasma levels were significantly upregulated when compared to children with H1N1 and mild symptoms." (PMID 33542685, 2020). "At 14 days post infection (directly after treatment) very high concentrations of IL-2, IL-13, IL-10, IFNγ, IL-6, and TNFα were observed." (PMID 32226027, 2020). "Transcription factors selected as biomarkers for targeting should be predicted for genes such as TLR7, TLR9, RHOA, IRF1, and IL6 since they are activated early in infection." (PMID 32872640, 2020). "There was a trend for overall increase in IL-6 transcript levels as the duration of infection increased." (PMID 32076422, 2020). "At 12 h post-infection with the virus, IL-6 and TNF-α were detectable in BMMCs (4.90% ± 0.67% and 10.4% ± 0.66%, respectively)." (PMID 33261178, 2020). "Infection and injuries to tissues can increase IL-6 production and generate a host inflammatory response by stimulating acute phase responses." (PMID 32848846, 2020). "AdV 7 infection of bronchial epithelial cell line and primary airway epithelial cells confirmed that AdV 7 increased IL-6 mRNA and protein expression in an infection dose-dependent manner." (PMID 33072092, 2020). "We observed that infection led to increased expression, particularly of IFNα, IFNγ, IL1β, and IL6 on day 1 post‐challenge." (PMID 32319216, 2020).
infection (continued). "IL-6 mRNA expression was significantly higher in koalas positive for both exogenous subtypes (KoRV-B and KoRV-C) than in those with endogenous infection only (KoRV-A; H6, KJ, KY, and KYB)." (PMID 33316950, 2020). "In this study a cut-off at 350 ng/L for IL-6 was used, which in general is a low threshold for infection." (PMID 33218324, 2020). "Infection with the mixture induced similar expression of IL-6 and IL-8 mRNA and protein to infection with F. nucleatum alone." (PMID 32244806, 2020). "The release of pro-inflammatory cytokines was determined in BAL samples collected at day 7 after infection, and concentrations of IL-1β, IL-6 and TNF-α were determined by multiplex immunoassay." (PMID 32899224, 2020). "SPRING revealed strong upregulation of IL-6 and the expression of this molecule was also strongly detected in bladder homogenates post-infection and by an antibody-based detection on bladder sections." (PMID 32112048, 2020). "Real time qPCR analysis of major pro‐inflammatory cytokines including IL‐1β, TNF‐α, and IL‐6 showed a less severe inflammatory response in the LL‐37‐Lung after infection." (PMID 31782624, 2020). "Interleukin 6 (IL-6), a pro-inflammatory cytokine, was released in reaction to infection and contributed in the host defense mechanism by generation of an acute stage immune response." (PMID 32228657, 2020). "On the contrary, IL-6 and TNFα were more expressed in infected supernatants, increasing concentration over the 3-day infection period." (PMID 32455939, 2020). "Both lymphopenia and elevated serum Il-6 levels are found in Ebola virus infection and are known to be inversely correlated with survival in patients post-infection and in mouse models of Ebola infection." (PMID 33071786, 2020). "There was a statistically significant difference noted in TNF-α, IL-1β and IL-6 mRNA expression at day 3 and day 7 compared to day 1 post-infection." (PMID 32391391, 2020). "The study also reported that IL-2, IL-6, IL-18, and GM-CSF were significantly higher during the acute stages of B. rossi-infection." (PMID 32133380, 2020). "Wild-type and IL6-KO mice were infected with B. abortus, and 1 week post-infection the number of macrophages, dendritic cells, and neutrophils was evaluated in the spleens by flow cytometry." (PMID 33322581, 2020). "The expression of genes related to Th1-related cytokines (TNF-α, IFN-γ, and IL-12p35) and Th17-related cytokines (IL-23 and IL-6) were significantly increased in canine PBMCs after 6 h post infection." (PMID 33520738, 2020). "We validate the establishment of suspended microscale (4 μL) infection cultures that secrete increased levels of proinflammatory factors IL-6, VEGF, and TNFα upon infection and form 3D aggregates (granuloma model) encapsulating the mycobacteria." (PMID 32974300, 2020). "CRP and WBC are well-known surrogate markers of infection, and are activated by interleukin-6 or tumour necrosis factor-alpha produced by monocytes or macrophages." (PMID 32706758, 2020). "IL-6 is involved in inflammation and infection responses as well as the regulation of metabolic, regenerative and neural processes." (PMID 32443433, 2020). "Both IL-6 and TNF-α can contribute to the elimination of Giardia, and IL-6 can modulate B cell maturation and induce antibody class switching to IgA during infection with Giardia." (PMID 32283818, 2020). "Reduced IL-1β and IL-6 levels were detected in the infected tracheal organ cultures, relative to infected trachea, at 24 h post infection, which is in agreement with the reduction in inflammatory response noted in the chicken PCLS during early culture." (PMID 31924278, 2020). "Intracerebral injection of IL-6 and adrenaline enhanced the severity of EV-A71 infection, while treatment with an anti-IL-6-neutralizing antibody or the adrenergic-antagonist phenoxybenzamine reversed the lethal effect of EV-A71 in neonatal mice." (PMID 31857694, 2020).
infection (continued). "When compared with SIRT3 WT BMDMs or PMs, SIRT3 KO BMDMs or PMs showed a significantly increased mRNA levels of Tnf, Il6, and Cxcl2 after infection with Mabc-R." (PMID 32835604, 2020). "IL-6 s in BALFs from MP mixed infection group were higher than those from control and MP single infection group." (PMID 32393186, 2020). "The infection by P. gingivalis markedly modulated IL-6 secretion with a steady and significant increase at 6 h post-infection, which also resulted in a large decline returning into baseline IL-6 levels at 24 h post-infection." (PMID 32419582, 2020). "IL6 is an important pleiotropic pro-inflammatory cytokine that plays key roles in infection, inflammation and haematopoiesis." (PMID 33236983, 2020). "Either IAL alone or in combination with penicillinG resulted in a significant decrease in TNF-α, IL-1β and IL-6 levels in the fluid at 36 h post infection." (PMID 32110983, 2020). "IL-6 is a pleiotropic cytokine showing a pro-inflammatory phenotype and is protective against infection." (PMID 33392105, 2020). "BTs increased from 35.0 °C–35.5 °C to 37.2 °C–39.0 °C, and the levels of plasma TNF-α and IL-6 increased after 24 h of infection in the three groups." (PMID 32221396, 2020). "We evaluated the production of TNF-α, IL-6 and IL-10 at different times from viral adsorption to 6 h and 24 h post infection." (PMID 32316163, 2020). "Instead, significant levels of IL-6 and IL-1β responses were observed at 24 and 48 h after infection with SARS-CoV-2, respectively." (PMID 33062077, 2020). "IL6 secretion was furthermore significantly reduced in response to heat-killed CHA 6 h post infection on protein level." (PMID 33250899, 2020). "There was a significant upregulation of pro-inflammatory cytokines, specifically IL-1β and IL-6, in challenged birds fed with normal starter formula (T2), at day 2 post-infection." (PMID 33260977, 2020). "S aureus has been reported to elicit a subtle immune reaction in the host after infection, through several mechanisms that include attenuation of NF-κB activation in mammary epithelial cells and TNFα, IL-6 and IL-8 in the mammary gland." (PMID 32071371, 2020). "A role for IL-6 for protective immune responses in experimental TB has been shown after a high dose intravenous infection with Mtb." (PMID 33375150, 2020). "As observed in SARS-Cov-1 and MERS, IL-6 is generated early in the infection as a result of innate, MyD88-dependent pathway, immune receptor activation following the detection of viral proteins inside the infected cell." (PMID 32961074, 2020). "Larvae that had recruitment of macrophages to the site of infection had significant increases for TNFα, interleukin-1-beta (IL1β), and interleukin-6 (IL-6), and this increase in expression in recruited larvae was independent of dissemination." (PMID 32776983, 2020). "Seven cytokines showed an increase in concentration that was dependent on the presence of localized infection: IL-1α, IL-1β, IL-6, IL-8, MCP-1, MIP-1α, and MIP-1β (p < 0.05)." (PMID 32867801, 2020). "Infection significantly influenced the release of only 4 out of the 22 measured cytokines: IL6, IL8, IL18, and MCP-1." (PMID 32664675, 2020). "Mice infected with Cr had increased expression of multiple cytokines including IL-17A, IL-22, IL-6, and IL-1β mRNA in colonic tissue 12 days after infection." (PMID 32230738, 2020). "Further verification using q-PCR indicated that IL6 and IL22 expression levels were unchanged during PmCQ2 infection, which implies that PmCQ2 causes a lower inflammatory response." (PMID 32851030, 2020). "K18-hACE2 SARS-CoV-2 infected mice showed elevated levels of Il6, Ccl2, and Cxcl10 at day 2 post-infection, which returned to baseline by day 5 post-infection." (PMID 33073694, 2020). "IL-6 KO mice showed enhanced bacterial numbers at 1 week post-infection compared to wild-type mice, whereas similar bacterial numbers were assessed at 6 weeks post-infection compared to infected wild-type mice." (PMID 33322581, 2020).